PGAP1 (post-GPI attachment to proteins inositol deacylase 1)
Description:
GPI inositol-deacylase that catalyzes the remove of the acyl chain linked to the 2-OH position of inositol ring from the GPI-anchored protein (GPI-AP) in the endoplasmic reticulum. Initiates the post-attachment remodeling phase of GPI-AP biogenesis and participates in endoplasmic reticulum (ER)-to-Golgi transport of GPI-anchored protein.
Synonyms: FLJ12377; Bst1; SPG67; ISPD3024; MRT42; NEDDSBA
Tractability: Antibody: UniProt predicts a signal peptide or a membrane-spanning region. PROTAC: ubiquitination databases record sites on it; its protein half-life has been measured.
Gene: Protein-coding gene on chromosome 2 (196,833,004 to 196,927,796, reverse strand). Ensembl gene ENSG00000197121.
Subcellular location: Endoplasmic reticulum membrane
Pathways (Reactome):
Metabolism of proteins: Attachment of GPI anchor to uPAR
Gene Ontology:
Molecular function: deacylase activity; hydrolase activity, acting on ester bonds
Biological process: attachment of GPI anchor to protein; GPI anchor biosynthetic process; positive regulation of ER to Golgi vesicle-mediated transport
Cellular component: endoplasmic reticulum; endoplasmic reticulum membrane
Genetic constraint (gnomAD): Loss-of-function variants: 19 observed, 40.36 expected, observed/expected ratio (o/e) 0.47, 90% interval 0.33 to 0.69. The upper end of that interval is the gene's LOEUF score, 0.69, which puts it in group 2 of 6, group 1 being the genes least tolerant of losing a copy. Missense variants: 456 observed, 525.02 expected, observed/expected ratio (o/e) 0.87, 90% interval 0.8 to 0.94. Synonymous variants: 175 observed, 191.12 expected, observed/expected ratio (o/e) 0.92, 90% interval 0.81 to 1.04.
Homologues: Orthologues: chimpanzee PGAP1 (99% identical), macaque PGAP1 (97% identical), rabbit PGAP1 (94% identical), dog PGAP1 (93% identical), pig PGAP1 (93% identical), mouse Pgap1 (90% identical), rat Pgap1 (88% identical), guinea pig PGAP1 (83% identical), zebrafish pgap1 (42% identical), Drosophila melanogaster PGAP1 (24% identical), Caenorhabditis elegans pgap-1 (15% identical). Paralogues in human: C2orf66 (3% identical).
Diseases named in the same sentence as PGAP1 in open-access papers:
PGAP1 is named in the same sentence as 30 diseases in open-access papers, as found by Europe PMC text mining. Sharing a sentence is not in itself a finding about the gene and the disease. The quoted sentences say what the papers report.
Encephalopathy (4 papers, 2014 to 2025). Encephalopathy is a term that means brain disease, damage, or malfunction. "Severe encephalopathy, characterized by epilepsy, spasticity and facial dysmorphism, has also been linked to PGAP1 pathogenic variants." (PMID 40785186, 2025). "This process has been implicated in brain disorders given the association of PGAP1 mutations with intellectual disability and encephalopathy in humans as well as severe developmental defects in forebrain formation in mice." (PMID 30664618, 2019). "This graphical abstract illustrates the comprehensive diagnostic approach, from next‐generation sequencing and bioinformatics to variant analysis and protein modelling, that led to the identification of a novel PGAP1 gene variant in an infant with neurodevelopmental delay and encephalopathy." (PMID 40785186, 2025). "Mutations in PGAP1 have been identified in one family of complex HSP (SPG67), but also in cases of intellectual disability and encephalopathy." (PMID 32180696, 2020). "In conclusion, null mutations in PGAP1 lead to severe intellectual disability and encephalopathy with no obvious malformations; we add PGAP1 to the growing number of genes involved in GPI-anchor deficiencies with human phenotypes." (PMID 24784135, 2014).
Intellectual disability (4 papers, 2014 to 2020). "In 2014 the first mutations, homozygous deletions c.589_591delCTT (p.Leu197del), in PGAP1 were described in siblings from Syria, floppy infants with developmental delay and severe intellectual disability." (PMID 27206732, 2016).
male infertility (3 papers, 2014 to 2023). The inability of the male to effect fertilization of an ovum after a specified period of unprotected intercourse. "In previous works, we have reported that Pgap1 knock-out mice had otocephaly, male infertility, growth retardation, and often died right after birth." (PMID 24784135, 2014). "Interestingly, Pgap1 has been detected in the proteome of mouse sperm and PGAP1 knockout mice showed male infertility." (PMID 37397249, 2023).
Brain atrophy (2 papers, 2016 to 2018). Partial or complete wasting (loss) of brain tissue that was once present. "Also, at least three splicing defective variants of PGAP1 (MIM 611655) have been reported in autosomal recessive mental retardation‐42 (MRT42, MIM 615802) and related syndromes with psychomotor retardation and brain atrophy as well as other features." (PMID 29974678, 2018).
microcephaly (2 papers, 2016 to 2025). A congenital or acquired developmental disorder in which the circumference of the head is smaller than normal for the person's age and sex. "In this study, we present a novel homozygous frameshift variant, p.(Val411Argfs*3), in the PGAP1 gene, associated with a severe neurodevelopmental phenotype characterized by corpus callosum agenesis, cerebellar hypoplasia, developmental and speech delays, microcephaly and seizures." (PMID 40785186, 2025).
cognitive decline (1 paper, 2025). "Our investigations reveal that aging differentially modulates restraint stress-induced ER stress responses: while suppressing the upregulation of protective ER stress-related genes (Fmo2, Creb3l1, Tmtc3, Bak1), it promotes the induction of Pgap1 change associated with cognitive decline." (PMID 41200271, 2025). "Upregulation of Pgap1, on the other hand, may exacerbate ER stress by disrupting GPI-anchored protein processing, impairing synaptic protein homeostasis, and depleting ER repair capacity, ultimately promoting neuronal injury and cognitive decline." (PMID 41200271, 2025).
developmental delay (1 paper, 2016). "Secondly an 8 years old boy from unrelated parents with muscular hypotonia, feeding difficulties and developmental delay who was shown to carry compound heterozygous c.274_276del (p.Pro92del) and c.921_925del (p.Lys308Asnfs*25) mutations in the PGAP1 gene." (PMID 27206732, 2016). "They discovered a homozygous splice site mutation (c.1952 + 1G > T) in PGAP1 in two male first degree cousins with global developmental delay, abnormal hand movements and increased deep tendon reflexes suggesting a motor neuron disease." (PMID 27206732, 2016). "Firstly a 3 year old boy from the United States with developmental delay and cortical visual impairment who was found to be compound heterozygous for two nonsense variants, c.1572 T > A (p.Tyr524*) and c.1396C > T (p.Gln466*) in PGAP1." (PMID 27206732, 2016).
holoprosencephaly (1 paper, 2014). Holoprosencephaly (HPE) is a complex brain malformation resulting from incomplete cleavage of the prosencephalon, occurring between the 18th and 28th day of gestation, and affecting both the forebrain and face, which results in neurological manifestations and facial anomalies of variable severity. "It was also indicated that the Pgap1 mutant mice phenotypes are dependent upon the genetic background since otocephaly and holoprosencephaly are not seen in some mouse strains." (PMID 24784135, 2014).
infertile (1 paper, 2024). "Impairment of PGAP1 activity leads to developmental diseases in humans and fatality and infertility in animals." (PMID 38167496, 2024). "Knockout (KO) of PGAP1 in C57BL/6 mice is lethal in most cases, and male survivors are infertile due to the inability of sperms to migrate from the uterus to the oviduct and attach to egg cells." (PMID 38167496, 2024).
schizophrenia (1 paper, 2019). A major psychotic disorder characterized by abnormalities in the perception or expression of reality. "In an ER enriched fraction, we observed decreased expression of PGAP1 (53 kD) [t = 2.17, p = 0.047] in schizophrenia." (PMID 30664618, 2019). "In total cortical homogenates, we observed decreased Tmp21 expression in schizophrenia, while in an ER-enriched fraction we observed decreased expression of the 53 kD isoform of PGAP1." (PMID 30664618, 2019). "While no change in PGAP1 protein expression was observed in total homogenate, we found decreased expression of PGAP1 in an ER-enriched fraction in schizophrenia." (PMID 30664618, 2019). "Neither haloperidol treatment nor PMI in these rodent experiments affected protein levels of Tmp21 or PGAP1 (53 kD), suggesting that the decreased expression of Tmp21 and PGAP1 (53 kD) observed in schizophrenia is not due to these factors." (PMID 30664618, 2019). "However, both PGAP1 and TMP21 are abnormally expressed in schizophrenia, consistent with abnormal GPI-AP processing and export." (PMID 30664618, 2019).
tumor (3 papers, 2021 to 2025). "PGAP1 can directly and/or indirectly induce carcinogenesis through tumor cell proliferation, migration, and resistance to multiple drugs." (PMID 34261404, 2021). "Furthermore, the pivotal nodes of the lncRNA–mRNA interaction network, including NEAT1, PGAP1, FKBP5 and CDON, were also validated by qRT–PCR and found to be downregulated in the EMPD tumor group." (PMID 34895219, 2021). "The three mRNAs, PGAP1, FKBP5 and CDON, may act as tumor suppressors in EMPD." (PMID 34895219, 2021).
infection (1 paper, 2025). The state of being infected such as from the introduction of a foreign agent such as serum, vaccine, antigenic substance or organism. "Indeed, knockdown of PGAP1 or PGAP3 with shRNAs could not inhibit Echo7 infection." (PMID 41252368, 2025).
neurodevelopmental disorder (1 paper, 2025). A behavioral and cognitive disorder with onset during the developmental period that involves impaired or aberrant development of intellectual, motor, or social functions. "Variants in the PGAP1 gene have been identified as causative factors for a range of phenotypes, primarily associated with neurodevelopmental disorders." (PMID 40785186, 2025). "PGAP1 gene variants are important in understanding GPI biosynthesis defects, which can lead to severe neurodevelopmental disorders like spastic paraplegia‐67." (PMID 40785186, 2025).
PGAP1 also shares sentences with these, for which no sentence is quoted: genetic diseases (2 papers); Alzheimer disease (1); autosomal recessive intellectual disability (1); Bardet-Biedl syndrome (1); brain disorder (1); breast carcinoma (1); CHIME syndrome (1); Cognitive impairment (1); epilepsy (1); glioblastoma (1); glycosylphosphatidylinositol deficiency (1); hemochromatosis of type 4 (1); melanoma (1); non-small cell lung carcinoma (1); osteoarthritis (1); prostate carcinoma (1); systemic sclerosis (1).